CCL2 (C-C motif chemokine ligand 2)
Diseases named in the same sentence as CCL2 in open-access papers (continued):
Sharing a sentence is not in itself a finding about the gene and the disease.
small cell lung carcinoma (6 papers, 2013 to 2025). Small cell lung cancer (SCLC) is a highly aggressive malignant neoplasm, accounting for 10-15% of lung cancer cases, characterized byrapid growth, and early metastasis. "For instance, macrophage infiltration in small-cell lung cancer (SCLC) is significantly decreased by epigenetic repression of CCL2 mediated by histone and DNA methylation." (PMID 37117649, 2023). "A study showed that the epigenetic silencing of CCL2 potentiates tumor development by repressing the macrophage infiltration in small cell lung cancer." (PMID 35675043, 2022). "Small cell lung cancer cells display high levels of monocyte chemoattractant protein-1 (MCP-1, also known as CCL2), which leads to increased recruitment of blood monocytes to tumors." (PMID 31611871, 2019). "In small cell lung cancer, DNA methyltransferase 1 (DNMT1) inhibits CCL2 expression by adding methyl groups to CpG islands in the promoter region of CCL2 gene, preventing TF binding." (PMID 41341593, 2025).
visceral leishmaniasis (6 papers, 2012 to 2025). A severe form of leishmaniasis characterized by irregular bouts of fever, substantial weight loss, swelling of the spleen and liver, and anemia (which may be serious). "In the context of L. infantum-induced visceral leishmaniasis, we assessed immune mediators including TNF, IL-1β, CXCL10, IL-12p70, IL-18, IL-23, and C-C motif chemokine ligand 2 (CCL2)." (PMID 40794782, 2025). "Validation of our DP cohort results revealed that CXCL10, but not CCL2, CCL5 or CXCL8 transcripts, were significantly upregulated by Leishmania infantum infection with or without clinically definite visceral leishmaniasis." (PMID 37601355, 2023).
acute myeloid leukemia (5 papers, 2021 to 2025). Acute myeloid leukemia (AML) is a group of neoplasms arising from precursor cells committed to the myeloid cell-line differentiation. "Studies of patients with acute myeloid leukemia have shown increased serum levels of CCL2 in comparison with healthy controls." (PMID 34646761, 2021). "However, plasma CCL2 levels in Acute myeloid leukemia (AML) patients are reported to be lower than those in healthy donors." (PMID 39850880, 2024). "There have been successful clinical applications of chemokine therapies, such as the CXCR4 antagonist AMD3100 for treating relapsed or refractory acute myeloid leukemia (AML) and the CCL2 inhibitor CNTO 888 for metastatic prostate cancer." (PMID 39206194, 2024). "In hematologic neoplasms, CCL2/CCR2 axis has been investigated in Acute Myeloid Leukemia (AML), multiple myeloma, and systemic mastocytosis." (PMID 37760903, 2023). "A significant secretion of CCL3, CCL2, CCL4, CXCL1, and CXCL8 exists in acute myeloid leukemia (AML) cells." (PMID 40148973, 2025).
allergic contact dermatitis (5 papers, 2014 to 2023). An inflammatory skin condition caused by an immune response to direct contact between the skin and an allergen. "For instance, in an animal model of allergic contact dermatitis, it has been shown that CCR2/CC-chemokine ligand 2 (CCL2) signaling is activated in skin neurons that promote itch behavior." (PMID 38116004, 2023). "The initial response to ticks suggested by this study is similar to an allergic contact dermatitis that is elicited by keratinocytes and fibroblasts producing IL-6, CXCL-8 and CCL-2 to recruit inflammatory leukocytes." (PMID 28143523, 2017).
anxiety disorder (5 papers, 2018 to 2024). A category of psychiatric disorders which are characterized by anxious feelings or fear often accompanied by physical symptoms associated with anxiety. "Reports have shown that cytokines such as interleukin (IL)-6, tumor necrosis factor-alpha (TNF-α), IL-10, and monocyte chemoattractant protein-1/CCL2 might be well associated with depressive, bipolar, or anxiety disorders." (PMID 29740354, 2018). "For CCL2, we observed that only patients with anxiety disorders (ANX subgroup) had significantly (P < 0.05) higher mRNA levels." (PMID 30504920, 2018).
Aortic dissection (5 papers, 2019 to 2025). Aortic dissection refers to a tear in the intimal layer of the aorta causing a separation between the intima and the medial layers of the aorta. "Moreover, CCL2 is significant in cardiovascular disease, which increases its applicability in the context of aortic dissection." (PMID 40342964, 2025).
bladder tumor (5 papers, 2016 to 2024). "Bladder tumors have been found to express high levels of M-CSF, capable of recruiting macrophages that express CCL2 and inducing M2 polarization." (PMID 39409924, 2024). "Specifically, bladder tumors leverage the upregulation of chemokines such as CCL2 and CXCL8 to attract immunosuppressive immune cells, thereby enhancing tumor growth and facilitating a more aggressive disease course." (PMID 39409924, 2024). "Specifically, CCL2 expression was correlated with shorter OS and increased mortality in T2 and luminal-type bladder tumors." (PMID 39409924, 2024). "To further dissect the CCL2 downstream signals involving the promotion of the BCa cell invasion, we examined the potential linkage of CCL2 regulation on the EMT signal pathways as early studies indicated that EMT is involved in the bladder tumor metastasis." (PMID 26556868, 2016). "Production of M2 polarizing cytokines such as CCL2, IL-10, and TGF-β by bladder tumors has been demonstrated in various in vitro studies and IL-10 production by bladder tumor cells has been shown to induce an immunosuppressive monocyte phenotype." (PMID 31824850, 2019).
Candida infection (5 papers, 2012 to 2024). "Expression of Ccl2 was unaffected by transgene expression, Candida infection or cytokine treatment at this time point after oral inoculation." (PMID 25344377, 2014). "In summary, these data establish CCL2/CCL7 as IFN-I-dependent chemokine signals driving the host response during systemic candidiasis." (PMID 22911155, 2012). "In summary, we demonstrated the protective role of Trim72 in antifungal responses by recruiting macrophages via enhancing cell migration capacity and upregulating CCL2 producing through NF-kB and ERK1/2 signaling during Candida infection." (PMID 39585917, 2024). "Ocular concentrations of IL-6, CXCL1/KC, CXCL2/MIP-2, and CCL2/MCP-1 were significantly elevated during C. albicans infection compared with non-albicans Candida infection by the reference strains." (PMID 30386320, 2018).
cardioembolic stroke (5 papers, 2021 to 2025). "The epidemiologic investigation uncovered that higher CCL2 levels in the blood and atherosclerotic plaques increases the risk of plaque vulnerability and cardioembolic stroke." (PMID 38794213, 2024). "It has been confirmed that genetically higher serum CCL2 concentration is associated with cardioembolic stroke." (PMID 35888126, 2022).
contact dermatitis (5 papers, 2015 to 2024). An inflammatory skin condition caused by direct contact between the skin and either an irritating substance or an allergen. "Mice deficient in CCL2 exhibited diminished recruitment of monocytes and eosinophils in an irritant contact dermatitis model." (PMID 38840912, 2024). "In a mouse model of contact dermatitis, decorin deficiency resulted in the reduced expression of chemokines, including KC/CXCL-1 and MCP-1/CCL2, and attenuated leukocyte recruitment." (PMID 25781946, 2015).
demyelination (5 papers, 2013 to 2024). "The analysis of chemotactic factors in cuprizone induced demyelination revealed an increased expression of CCL-2, CXCL-10, and HGF in the corpus callosum suggesting a potential source of the CNS to attract MSC into the lesion." (PMID 23922802, 2013). "In addition, CCL2 has an important role in attracting monocyte/macrophages into the CNS that increases demyelination severity." (PMID 38879499, 2024). "M. leprae induces neural demyelination by stimulating the production of matrix metalloproteinases (MMPs), C-X-C motif chemokine ligand 10 (CXCL10) and C-C motif chemokine 2 (CCL2), which attract macrophages." (PMID 36326715, 2022). "Immunization with MOG peptide, i.e., induction of EAE during CPZ-induced demyelination resulted in microglia activation in contrast to classic EAE, and also potentiated gene expression of CXCL10, CCL2, and CCL3 in the corpus callosum beside additional brain areas." (PMID 32582192, 2020).
diffuse cutaneous Leishmaniasis (5 papers, 2012 to 2022). A form of LEISHMANIASIS, CUTANEOUS caused by Leishmania aethiopica in Ethiopia and Kenya, L. pifanoi in Venezuela, L. braziliensis in South America, and L. mexicana in Central America. "In humans, CCL2 expression correlated with self healing cutaneous lesions, whereas CCL3 was associated with lesions of chronic progressive diffuse cutaneous leishmaniasis caused by L. mexicana." (PMID 22679519, 2012). "The expression of CCL2 and CXCL9 was higher in CL tissue cells than in diffuse cutaneous leishmaniasis tissue." (PMID 22458474, 2012).
disc degeneration (5 papers, 2018 to 2025). "Elevated β‐catenin and CCL2 levels in Sox9‐deleted tissues suggest that the β‐catenin‐CCL2 pathway plays a crucial role in the inflammatory response and pain associated with disc degeneration." (PMID 40012719, 2025). "Deletion of Sox9 in Aggrecan‐expressing IVD tissues affects disc degeneration and associated pain behaviors through the β–catenin–CCL2 pathway." (PMID 40012719, 2025). "Nucleus pulposus cells produce an array of chemokines, including Ccl2 (Mcp-1), Ccl7, and Ccl8, and their expression levels connect with the severity of disc degeneration; chemokine serum levels likewise associate with disease severity." (PMID 36674887, 2023). "Our findings reveal that the disruption of Sox9 enhances β‐catenin activity and CCL2 expression, contributing to disc degeneration." (PMID 40012719, 2025). "Targeting the CCL2/ICAM1 pathways may be pivotal in the preventive treatment of inflammatory responses that aggravate the process of disc degeneration." (PMID 30585203, 2018). "Our results showed that CCL2 is also increased in Sox9‐deleted tissues, suggesting that the dysregulation of the β–catenin–CCL2 pathway due to Sox9 deletion may drive the inflammatory response and pain observed in degenerative disc disease." (PMID 40012719, 2025). "The enhancement of CCL2-dependent ICAM1 expression occurs through the JAK1/FAK/ERK/GSK3 and PKCδ signaling pathways in AF cells, which may contribute to immune cell recruitment and disc degenerative diseases." (PMID 30585203, 2018).
ductal carcinomas (5 papers, 2011 to 2022). "Overall, these data indicated that ductal carcinomas with high CCR2 expression were associated with increased invasiveness and increased expression of CCL2, phospho-SMAD3 and phospho-p42/44MAPK." (PMID 33888841, 2021).
fibrosarcoma (5 papers, 2015 to 2023). A malignant mesenchymal fibroblastic neoplasm affecting the soft tissue and bone. "In the murine MCA203 fibrosarcoma model, CCL2 was identified as a crucial chemokine recruiting MDSCs in the spleen in a CCR2-dependent manner." (PMID 37210553, 2023). "Fibrosarcoma cells responded to poly(I:C) exposure with significant production of CCL2 (p < 0.05) that was amplified with transfection." (PMID 35737804, 2022). "Additionally, the development of mechanical allodynia was blocked in neuropathic CCR2 knockout mice, and the treatment of DRG neurons in vitro with CCL2 obtained from fibrosarcoma culture supernatants increased the amount of mRNA for the Cavα2δ1 subunit." (PMID 34575835, 2021).
Hashimoto thyroiditis (5 papers, 2019 to 2025). An autoimmune disorder caused by the production of autoantibodies against thyroid tissue. "Similarly, H3K4me3, an activating histone modification, was detected in Hashimoto's thyroiditis to enrich the promoter region of CCL2 and resulted in persistent up‐regulation of CCL2 expression of thyroid follicular cells." (PMID 36872292, 2023). "Increased expression of chemokines like CCL2 and CCL3 in Hashimoto’s thyroiditis patients suggests their role in inflammatory responses and tissue damage by attracting immune cells to the thyroid gland." (PMID 40837371, 2025).
Headache (5 papers, 2020 to 2026). Cephalgia, or pain sensed in various parts of the head, not confined to the area of distribution of any nerve. "We found that increased CCL2 level is an independent risk for more headache impact on lives in patients with mTBI." (PMID 33228537, 2020). "The independent factor was CCL2 levels, and dependent variable was headache impact severity indicated by the HIT-6, with identified GM volume alterations as mediators." (PMID 33228537, 2020). "In this study, we asked whether repeated sumatriptan administration in mice alters the level of CCL2 and CCR2 mRNA expression in dura and trigeminal ganglion (TG), tissues that are strongly implicated in headache generation." (PMID 39528947, 2024). "Our previous work shows that the interaction between peripheral CCL2 and CGRP signal pathways plays a pivotal role in nitric oxide signaling-induced headache chronification." (PMID 39528947, 2024).
HIV-associated neurocognitive disorder (5 papers, 2012 to 2026). HIV-associated neurocognitive disorder (HAND) remains a common complication of HIV infection in the combination antiretroviral therapy (ART) era. "Homozygosity for the CCL2-2518 G allele, which leads to increased CCL2 expression, was associated with a 50% reduction of the risk of acquiring HIV, although after infection this genotype enhanced disease progression and the risk of HIV-associated neurocognitive disorders (HAND)." (PMID 31377844, 2019).
ileitis (5 papers, 2011 to 2024). "Other factors that were only increased in the BALF of SHIP-1−/− mice with ileitis were IL-33 and TNFα, while IL-6, CCL2, and CCL4 were more significantly increased in the lungs of SHIP-1−/− mice with ileitis." (PMID 39432107, 2024).
inflammatory skin disease (5 papers, 2012 to 2025). Inflammatory skin disorders covers a broad category that includes many conditions ranging in severity, from mild itching to grave medical health complications These disorders are common in people of all ages and races. "Although we show only a slight reduction in IL–1β release, OSB‐specific VOCs induced a significant decrease of CCL2, a key chemokine involved in monocyte/macrophage infiltration in inflammatory skin diseases, a hint towards potential beneficial effects of OSB emissions in humans." (PMID 40114338, 2025).
leiomyoma (5 papers, 2013 to 2023). A well-circumscribed benign smooth muscle neoplasm characterized by the presence of spindle cells with cigar-shaped nuclei, interlacing fascicles, and a whorled pattern. "Many proteins such as F3, WNT2, CDH1, and LIF shown in the protein–protein interaction networks are well known in leiomyoma pathogenesis, and others, such as ICAM1, CXCL8, CCL2, and NANOG are novel and require further investigation." (PMID 36835153, 2023).
lung squamous cell carcinoma (5 papers, 2021 to 2025). "Nevertheless, researchers noticed that high CCL2 expression was associated with favourable overall survival and progression‐free survival in patients with lung squamous cell carcinoma (LUSC)." (PMID 34464477, 2021). "By contrast, KRAS/CCL2/IL1B expression did not impact the survival of patients with squamous cell lung carcinoma (a tumor with low KRAS mutation frequency) (upper right)." (PMID 35327394, 2022).
Lyme disease (5 papers, 2021 to 2025). Lyme disease (named after the towns in the USA where the disease was first identified) is a bacterial infection caused by Borrelia burgdorferi. "Oligodendrocytes secrete cytokines such as C-C motif chemokine ligand 2 (CCL-2) and IL-8 in response to neuroborreliosis, the neurological manifestation of Lyme’s disease." (PMID 34602982, 2021). "Bulk RNA-seq analysis of infected mouse skin tissues further show that cheA1mut fails to elicit mouse tnf-α, il-10, il-1β, and ccl2 expression, four important cytokines for Lyme disease development and B. burgdorferi transmigration." (PMID 38011206, 2023). "The transcript levels of several important cytokines and chemokines that have been reported to contribute to Lyme disease progression, such as IL-10, IL-1β, TNF-α, and CCL2, were upregulated in the WT- but not MT-infected tissues, which was validated by qRT-PCR." (PMID 38011206, 2023).
metastatic prostate carcinoma (5 papers, 2019 to 2024). A carcinoma that arises from the prostate gland and has spread to other anatomic sites. "Clinical trial using carlumab monotherapy, a human IgG1k monoclonal antibody against CCL2, had little success in patients with advanced solid tumors and metastatic prostate cancer, however, results from CCL2 blockade with immune checkpoint blockade have yet to be reported." (PMID 34976006, 2021). "However, targeting CCL2 with the humanized monoclonal CCL2 neutralizing antibody CNTO 888 in a phase I trial (NCT00537368) in solid tumors and in a phase II trial (NCT00992186) in metastatic prostate cancer, was unsuccessful due to ineffectiveness of CNTO 888 in reducing CCL2 serum level." (PMID 30894861, 2019).
neuritis (5 papers, 2013 to 2026). A neuropathy arising from inflammation of one or more nerves. "Moreover, CCL2 can attract CCR2‐positive macrophages to the immune microenvironment of neuritis, where they promote neural invasion by activating RET signaling in cancer cells." (PMID 41556039, 2026). "43% of patients presented neuropathic pain and no one had neuritis TGF-beta, IL-17, CCl-2 and IP-10." (PMID 38116016, 2023). "The concentrations of CCL-2/MCP-1, IFN-γ and, CXCL10 / IP-10 were slightly higher in patients with neuropathic pain, as opposed to those with neuritis." (PMID 32038662, 2020).
Pain (5 papers, 2012 to 2022). An unpleasant sensory and emotional experience associated with actual or potential tissue damage, or described in terms of such damage. "In the context of neuropathic pain, minocycline blocked microglial activation, inhibited CCL2-induced potentiation of glutamatergic transmission in substantia gelatinosa neurons, and attenuated hyperalgesia induced by spinal injection of CCL2." (PMID 34857006, 2021). "As the significant upregulation of CCL2 and CCR2 was observed from day 3 after IAMNT, we speculate CCL2-CCR2 signaling may be involved the maintenance rather than the development of the trigeminal neuropathic pain." (PMID 22721162, 2012).
pneumococcal infection (5 papers, 2017 to 2023). Infections with bacteria of the species streptococcus pneumoniae. "The deficiency of MIF was associated with reduced numbers of macrophages, as well as an impaired upregulation of CCL2 in the respiratory tract, highlighting the role of this immune mechanism in the protection against pneumococcal infection." (PMID 37958756, 2023). "Now, in the pneumococcal infection model, we observed impaired protection against infection, despite increased concentrations of inflammatory cytokines, and monocyte chemokines (CCL2)." (PMID 34464475, 2021).
pneumococcal meningitis (5 papers, 2013 to 2019). An acute purulent infection of the meninges and subarachnoid space caused by Streptococcus pneumoniae, most prevalent in children and adults over the age of 60. "Our present findings are congruous with those of Klein and colleagues, who similarly report lesser increases in IL-1β, but comparable concentrations of CCL2 and IL-6, within the brains of TLR2/4 double GKO mice in a pneumococcal meningitis model." (PMID 31700009, 2019). "In vitro, antibodies against CCL2, CCL3, and CCL4 inhibited monocyte chemotactic properties of CSF from patients with pneumococcal meningitis." (PMID 23997430, 2013). "Patients with pneumococcal meningitis show high levels of pro-inflammatory cytokines such as TNF-α, IL-1β, IFN-γ, IL-2, IL-6 and IL-12, anti-inflammatory cytokines (IL-10 and TGF-β) and chemokines such as CXCL8 (IL-8) CCL3 (MIP-1a) and CCL2 (MCP-1) in their CSF." (PMID 26744349, 2016).